CD4 (CD4 molecule)
Diseases named in the same sentence as CD4 in open-access papers (continued):
Sharing a sentence is not in itself a finding about the gene and the disease.
infection (continued). "Longitudinal qPCR analysis of the 12 strains after LCMV Cl-13 infection revealed only minor differences between the CD4 depleted and the isotype treated OMM12 group early after infection which is possibly attributable to a stress response." (PMID 40274773, 2025). "Spike-specific CD4 and CD8 T cells expand more rapidly in vaccinated individuals with breakthrough Omicron variant infections who more effectively control SARS-CoV-2 viral load compared to unvaccinated individuals." (PMID 40472803, 2025). "Specifically, introducing CD4+ T cells at days –1 or 3 after infection reduced bacterial burdens in Rag1–/– mice, whereas delaying T cell transfer until day 7, when a mature biofilm has formed, was not protective." (PMID 39989461, 2025). "While CD4 + Naïve cells comprised the second highest proportion of infected cells at 29%, they are an abundant cell type in the blood and the overall infection rate was much lower (2.2%)." (PMID 40386405, 2025). "It is likely that the killing of uninfected bystander CD4+ T cells often results in failed infections, thereby preventing HIV-1 replication and dissemination." (PMID 40072080, 2025). "An Ehrlichia chaffeensis canine vaccine and infection model demonstrated similar findings where DP T cells were the dominant responding subset by proliferation assay, followed by CD4+ T cells." (PMID 40354406, 2025). "We carried out ex vivo SmartSeq2 to analyse the gene expression and the TCR of spike-specific CD4+ T cells from individuals at both 1–3 months and 3–4 years after infection." (PMID 41034205, 2025). "This site also has higher levels of activated CD4+ T cells than blood, which are suitable targets for infection." (PMID 40438119, 2025). "Seven major T and natural killer (NK) cell clusters were identified, including a population resembling naïve, circulating CD4+ T cells (T cell CD4 Ccr7) that decreased in frequency as infection progressed in both mouse strains, albeit earlier in C57BL/6 mice." (PMID 40986319, 2025). "Treg cells, by contrast, are immunosuppressive CD4+ T cells that follow a different trajectory during infection." (PMID 41009690, 2025). "Next, we leveraged the longitudinal aspect of MUSICAL to study CD4+ T cell subset dynamics over the course of symptomatic and asymptomatic infections." (PMID 41000872, 2025). "In a mouse model infected with mismatched serotypes of Streptococcus pneumoniae, prior infection led to the seeding of CD4+ TRM cells in previously infected lung lobes." (PMID 39802636, 2025). "In PLWH, significant epigenetic acceleration has been observed, correlating with infection duration, CD4+ nadir, and persistent systemic inflammation." (PMID 41153793, 2025). "In the later stages of the infection, the proliferation rate of naive CD4+ T cells further increases, shifting the selection pressure in favor of X4 variants." (PMID 40709192, 2025). "While antibodies are likely to help augment effective immunity, better understanding the T cell antigens that drive effective CD4+ T cell responses during Mab infection will need to be explored in detail in the future." (PMID 40415550, 2025). "The frequency of infection of naive CD4+ T cells from participant 1001 was the highest of all participants, representing 40% of the total infected peripheral CD4+ T cells in this donor." (PMID 40048262, 2025). "Conversely, a decrease in blood CD4+ Tregs, which includes both CD4+CD8α+ and CD4+CD8α− Tregs, was found in infections with CADC_HN09." (PMID 41510007, 2025). "The PCA analysis integrating all aspects of immune phenotype for both CD4 and CD8 T cells further demonstrated the global impact of transplantation and the association with infection across T cell phenotypes." (PMID 40475763, 2025). "The production of IFN-γ, TNF, and IL-10 was reduced in the draining lymph node, as well as the total number of CD3+CD4+IFN+ and CD3+CD4+TNF+ T cells in the infection site." (PMID 40982482, 2025).
infection (continued). "During acute infection, we found that the CD4 + effector memory cells, were relatively decreased (from 32.1–14.5%)." (PMID 40386405, 2025). "Recently, beyond the multifunctionality of vaccine-specific CD4+ T cells, Trms have demonstrated an ability to enhance the adaptive immune response to various pathogens and improve infection control." (PMID 40414893, 2025). "By stage, the single missing VL occurred in long-term infection, and the single missing CD4 occurred in EARLY infection." (PMID 41229481, 2025). "Differences between these stages of infection can be attributed to differing CD4+ T cell birth and death dynamics but consistently relate to HIV being a passenger within CD4+ T cell proliferative clones." (PMID 40464563, 2025). "neoformans, with a positive antigen titer (1:32) consistent with active infection despite the patient’s normal CD4 count (641 cells/mm3)." (PMID 41541964, 2025). "CD4+ T cells are generally believed to provide protective immunity against Mtb by recruiting the Th1 cell population at the site of infection, although some evidence also suggests a role for CD8+ cells." (PMID 39949767, 2025). "The production of IL-10 and the inhibition of IL-17 secretion (related to the resolution of infection) by CD4+ T cells in humans are stimulated by IL-27." (PMID 41361890, 2025). "Regarding changes in T lymphocyte subpopulations, we observed that the levels of CD3+CD4+ T lymphocytes in WCCs were consistently higher than those in RWFCs, both pre- and post-infection." (PMID 40941329, 2025). "Frequencies of naive CD4+ T cell infection varied among participants and were markedly lower than those determined for memory CD4+ T cells, in agreement with previously reported measurements from adult samples." (PMID 40048262, 2025). "To address this, we employed a set of T/F and chronic HIV-1 strains to evaluate their infection efficiency in primary macrophages and the impact of autologous CD4+ T cell coculture." (PMID 40130873, 2025). "The absence of an association between behavioral factors and baseline viral load or CD4 count suggests that demographic variables and infection stage play a more prominent role than substance use in determining immunological status at diagnosis." (PMID 41229481, 2025). "In this study, we report on the dynamic phenotypes of CD4+ T-cells responding to infection which differ profoundly between mice bearing different MHC-II alleles." (PMID 40873577, 2025). "Prior studies demonstrate that antigen-induced CD4+ T cells confer protection in murine infection models." (PMID 40563867, 2025). "Five days post-infection, a time point characterized by notable expansion of Ag-specific CD4+ T cells, we performed the isolation and FACS-based sorting of Smarta CD4+ T cells from footpad-draining popliteal lymph nodes (dLNs)." (PMID 40169810, 2025). "In this model, immunocompromised Rag1−/− mice, lacking T and B cells, are intranasally infected with Cryptococcus neoformans (Cn) serotype A H99 (CnH99), followed by intravenous CD4+ T cell reconstitution three weeks post-infection." (PMID 41301925, 2025). "In contrast, replication of all strains was readily detectable in CD4+ T cells analyzed at 4 days post-infection." (PMID 40130873, 2025). "It occurs 72 h after initial infection as de novo-produced virions bud from the DC plasma membrane and infect CD4 T cells as they interact with DCs via a virological synapse." (PMID 39861894, 2025). "For example, proinflammatory cytokines can in some cases increase viral replication in Langerhans cells or promote their capture of viruses and subsequent trans-infection of CD4+ T cells." (PMID 39854613, 2025). "We also show that CD4+ T cell precursors against Eng2 were detectable in naive individuals and that patients who had recovered from these infections evinced a memory and recall CD4+ T cell response to Eng2 and its immunodominant epitopes that we have mapped." (PMID 41061037, 2025).
infection (continued). "Here, this study analyzes HIV-1-infected CD4+ T cells from peripheral blood mononuclear cells from people living with HIV-1 during early infection (<6 months) using single-cell RNA and ATAC sequencing." (PMID 40838493, 2025). "The abundance of IFN-γ in the lungs was 10-fold lower in CD4+ T cell-depleted compared to isotype antibody-treated mice at 3 weeks post-infection, consistent with prior reports." (PMID 40489538, 2025). "In the early stages of infection, the number of CD4+ T cells decreases sharply, resulting in immune system damage." (PMID 40070826, 2025). "CD4+ T cells were critical for infection containment as anti-CD4 treatment significantly increased bacterial burdens across all tissues examined." (PMID 39989461, 2025). "MDV reactivation in CD4+ αβ T-cells initiates a late cytolytic and immunosuppressive phase from 2- to 3-weeks post-infection." (PMID 40733625, 2025). "It is suggested that a proportion of cells in each population survive contraction and become CD4+ TM cells following infection elimination." (PMID 40391228, 2025). "We isolated CD4+ T cells from blood collected from three healthy donors and performed infection with DuoFluo HIV." (PMID 41012705, 2025). "Consistent with impaired T cell recruitment to sites of infection in Ccr2–/– and Rag1–/– mice, antibody-mediated depletion of CD4+ or CD8+ T cells from WT mice diminished paralysis." (PMID 40459936, 2025). "CD4+ T cells, also integral to adaptive immunity, help coordinate immune responses by stimulating other immune cells, such as macrophages, to combat infections." (PMID 41142813, 2025). "This underscores HIV-1’s ability to persist in memory CD4+ T cells and evade host antiviral responses early in infection." (PMID 40838493, 2025). "This was accompanied by increased early bacterial loads and lesion formation in infected C57BL/6 mice, prior to the accumulation of large numbers of effector CD4+ T cells in lung lesions and their eventual superior control of infection." (PMID 40986319, 2025). "In summary, the progeny of the transferred CD4+ T cell fractions that were sorted according to T-bet reporter levels all exhibited multiple phenotypical features of exhaustion by day 7 of infection with LCMV Cl13." (PMID 41488650, 2025). "Third, CD4+ T cells are recruited from peripheral circulation to infection sites to participate in antiviral responses, resulting in transient reduction of circulating CD4+ T cells." (PMID 41448851, 2025). "The diminished expression of the CD4 gene in severe cases during infection is in line with previous studies and supports our observation of reduced numbers of circulating CD4+ cells." (PMID 40766325, 2025). "Correspondingly, we observed a decrease in the frequency of POSH cKO cells and an increase in WT POSH-sufficient donor cells on days 15 and 28 post-infection in mice transferred with OT1 POSHfl/fl CD4-Cre CD8 T cells." (PMID 40672960, 2025). "While the frequency of the CD38+CD19+ B cell population declined rapidly after the first day, the frequency of the CD38+CD4+ T cell population remained relatively stable throughout the first week post-infection." (PMID 40733503, 2025). "It is possible that a more robust IFN response in adults is effectively clearing virus early in infection leading to these weaker CD4 and neutralizing antibody responses." (PMID 40360698, 2025). "The CD4/CD8 ratio decreased after infection, likely reflecting the strong priming of cytotoxic T cells following WE-CL13-GP181M-185W-492I administration." (PMID 41086811, 2025). "CD4 T cells isolated after clearance of the acute infections or during the chronic phase of the LCMV Cl13 infection demonstrated a responsiveness to IL‐12 and IL‐18 stimulation by IFN‐γ production, regardless of their respective pathogen encounter." (PMID 40923840, 2025).
infection (continued). "Three of these clusters, measured as a proportion of their parental CD4+ or CD8+ populations, correlated with a reduced risk of grade ≥3 infection, grade ≥3 second primary malignancy (SPM) and death, respectively." (PMID 40313965, 2025). "In this infection model, CD4+ T cells exhibited a differentiation bias toward TFH cells, which participate in the formation of germinal centers (GC) and promote B cell somatic hypermutation and antibody production." (PMID 40777021, 2025). "Notably, most in vitro infection studies and associated screening approaches are initiated using cell lines, as they are easier to handle and not affected by donor variability, as compared to primary cell systems in general and human CD4+ T cells in particular." (PMID 40911682, 2025). "One complicating factor in CD4+ T cell exhaustion is its heterogeneity, as some CD4+ T cells become functionally inactivated early in infection, whereas others remain functional throughout infection." (PMID 40777021, 2025). "Our findings indicatedthat FAK activation in CD4+ T cells occurred within 30 minpost-infection, paralleling the observed changes in the actin cytoskeleton." (PMID 40094365, 2025). "The IRF4 level remained relatively high in CD19+ B cells during the establishment of lymphoblastoid cell lines (LCLs) but gradually declined in CD4+ T cells and remained at a low level until CD4+ T cells disappeared approximately two weeks post-infection." (PMID 40733503, 2025). "MDV confronts primary target cells (B lymphocytes and activated CD4+ T lymphocytes) and reaches replication peak from three to 7 days post-infection." (PMID 40241721, 2025). "This was attributed to impaired immune responses, particularly in CD4+ T cells, which are critical for combating infections." (PMID 39903705, 2025). "Abundance of CD4+ T cells and CD4+ T cell–macrophage contacts within lesions was also increased at 26 days after infection in anti-IFNAR–treated C3HeB/FeJ mice, concurrent with the high degree of protection observed at this time point." (PMID 40986319, 2025). "CD4+ T cells have been established as central orchestrators of cellular and humoral immune responses to infection or vaccination." (PMID 39604225, 2025). "Second, we were unable to apply the full recent infection testing algorithm, which includes CD4 + lymphocyte counts and HIV RNA quantification (viral load), due to limited access to these clinical data from public health databases." (PMID 41268394, 2025). "It was also surprising to observe that adult macaques had very modest activated CD4+ T cell responses throughout infection." (PMID 40360698, 2025). "Third, the sample size was insufficient to perform detailed subgroup analyses (e.g., examining individuals with CD4+ < 200 cells/mm3 or those who developed hybrid immunity through prior infection)." (PMID 40432092, 2025). "GATA3+CD4+ Th2 memory cells persist in the peritoneal cavity and small intestinal lamina propria after natural murine infection with Heligmosomoides polygyrus." (PMID 39802636, 2025). "Many infected T cells have been found to co-express CD4, CCR6, and the transcription factor RORγt, suggesting the Th17 lineage is implicated in infection." (PMID 39854613, 2025). "Studies have shown that SARS-CoV-2–specific cellular immune responses remained detectable in recovered patients 8 months after infection, although higher in CD4+ T cells than in CD8+ T cells, which agrees with our data." (PMID 40378227, 2025). "Specifically, we observed lower BTLA expression on resting CD4+ T cells during both acute and chronic infection phases in ECs (49, 84, and 133 days post-infection) while maintaining comparable IC expression levels on resting CD4+ TCM relative to PGs." (PMID 40637373, 2025).
infection (continued). "In summary, our results demonstrate for the first time to our knowledge that preexisting CD4+ and CD8+ Temra cells are significantly associated with subsequent inapparent infection outcome, particularly in those with a history of repeated exposure." (PMID 39989460, 2025). "For the CD4 EM subtype expressing CD25, decreased frequency prior to transplant was associated with infection (p=0.056), although this observation only reached statistical significance with correction for patient age (p=0.019) (Pre)." (PMID 40475763, 2025). "The number of IFN‐γ‐producing CD8+ T cells and TNF‐α‐producing CD4+ T cells was significantly higher in the 1–5 years group after infection, compared to the 6–10 years group after recovery (p = < 0.0001)." (PMID 39822038, 2025). "One possibility for this pattern of decay is infection of two different types of cells (suggested previously to be CD4+ T cells and macrophages), with different turnovers giving rise to the biphasic decline." (PMID 41467837, 2025). "Infections were more common among participants with normal/high CD4 counts (18.8%) compared to those with moderate (12.5%) or severely low CD4 counts (68.8%), though the differences were not statistically significant (p = 0.951)." (PMID 39860354, 2025). "Repeated controlled human Schistosoma mansoni infection, designed to reflect the reinfection cycles common in endemic areas, shows that repeated exposure induces mixed worm-specific CD4+ T cell responses similar to those seen in endemic infection." (PMID 40707512, 2025). "This indicates that IgA and CD4 T-cells were generated following immune system stimulation due to infection or vaccination." (PMID 41280926, 2025). "Following activation and infection of freshly isolated CD4+ T cells, these cells can be maintained in culture for only a few weeks, with a need for re-stimulation to propagate them further." (PMID 41509258, 2025). "IL-2 and its receptor are important in the proliferation and differentiation of CD4+ lymphocytes, specifically of naïve to helper T-cell subtypes following infection." (PMID 41148718, 2025). "This contrasted with the peritoneum where CD4+ T cell numbers were diminished at the peak of infection and showed a significant decrease at day 11 in the mutants." (PMID 41191641, 2025). "infection, with contributions of CD4+ T cells to the outcome of active disease and CD8+ cells contributing to immune protection." (PMID 40096173, 2025). "In contrast, the T cell CD4 Ifng and T/NK Prolif clusters increased in frequency earlier and to a greater degree during infection in C57BL/6 than C3HeB/FeJ mice." (PMID 40986319, 2025). "HIV-1 particles are captured by the immunoglobulin superfamily member Siglec-1 on the surface of macrophages and dendritic cells, leading to particle internalization and facilitating trans-infection of CD4+ T cells." (PMID 40067817, 2025). "During the process of TB, innate immune macrophages and adaptive immune CD4+ T lymphocytes play crucial roles in controlling infection." (PMID 40170749, 2025). "Our findings show that the immunity level is compromised as early as 7 days after SIV infection, with a rapid increase in SIV copies per mL and a significant drop in the CD4/CD8 ratio within the first 14 days of infection." (PMID 40093003, 2025). "Rebound in CD4+ T cell frequency was observed in all HIV-C animals that had also shown CD4+ T cell depletion in the infection phase." (PMID 40308596, 2025). "We also reveal the potential of ARG2 inhibition to restore CD4+ T cell and enhance resistance to secondary infections." (PMID 40860137, 2025). "Concernant l'infection par VIH, le taux de CD4 initial ou lors du diagnostic de cette association, la/les affection(s) opportuniste(s) lors ou précédant le diagnostic, le traitement antirétroviral initié (première ou seconde ligne) étaient précisés." (PMID 40070975, 2024).